TBC1D32 (TBC1 domain family member 32)
Description:
Required for high-level Shh responses in the developing neural tube. Together with CDK20, controls the structure of the primary cilium by coordinating assembly of the ciliary membrane and axoneme, allowing GLI2 to be properly activated in response to Shh signaling (By similarity).
Synonyms: BROMI; C6orf170; C6orf171; FLJ30899; dJ310J6.1; FLJ34235; bA57L9.1; ALHSA; OFD9; RP100
Tractability: PROTAC: ubiquitination databases record sites on it.
Gene: Protein-coding gene on chromosome 6 (121,079,494 to 121,334,745, reverse strand). Ensembl gene ENSG00000146350.
Subcellular location: Cytoplasm; Cell projection, cilium
Subcellular location (Human Protein Atlas): Cytosol; Mitochondria; Vesicles
Gene Ontology:
Molecular function: protein binding
Biological process: retinal pigment epithelium development; non-motile cilium assembly
Cellular component: cytoplasm; cilium
Genetic constraint (gnomAD): Loss-of-function variants: 87 observed, 105.68 expected, observed/expected ratio (o/e) 0.82, 90% interval 0.69 to 0.98. The upper end of that interval is the gene's LOEUF score, 0.98, which puts it in group 4 of 6, group 1 being the genes least tolerant of losing a copy. Missense variants: 976 observed, 1,029.9 expected, observed/expected ratio (o/e) 0.95, 90% interval 0.9 to 1. Synonymous variants: 358 observed, 352.23 expected, observed/expected ratio (o/e) 1.02, 90% interval 0.93 to 1.11.
Gene-disease validity (ClinGen):
ClinGen rates the evidence that TBC1D32 causes each of these diseases.
ciliopathy (autosomal recessive): Definitive. A genetic disorder of the cellular cilia or the cilia anchoring structures, the basal bodies, or of ciliary function.
Homologues: Orthologues: chimpanzee TBC1D32 (99% identical), macaque TBC1D32 (95% identical), dog TBC1D32 (88% identical), pig TBC1D32 (88% identical), mouse Tbc1d32 (85% identical), rat Tbc1d32 (84% identical), rabbit TBC1D32 (81% identical), guinea pig TBC1D32 (75% identical), tropical clawed frog tbc1d32 (62% identical), zebrafish tbc1d32 (56% identical), Caenorhabditis elegans T01G9.2 (5% identical). Paralogues in human: PHAF1 (8% identical).
Diseases named in the same sentence as TBC1D32 in open-access papers:
TBC1D32 is named in the same sentence as 24 diseases in open-access papers, as found by Europe PMC text mining. Sharing a sentence is not in itself a finding about the gene and the disease. The quoted sentences say what the papers report.
ciliopathies (6 papers, 2021 to 2023). "Mutations in CDK20 and TBC1D32 are associated with ciliopathies and defective embryonic development resulting from the dysregulation of Hh signaling." (PMID 37545519, 2023). "This is supported by the zebrafish tbc1d32 morphant model that shows dose-dependent ciliary defects in the distal kidney tubules and the association of renal anomalies with other ciliopathies." (PMID 37768732, 2023). "Subsequently, 7 patients from 5 families were reported as carrying different pathogenic TBC1D32 variants and presenting with syndromic ciliopathies." (PMID 37768732, 2023). "Along this line, a recent study described developmental cochlear defects in the knockout Tbc1d32 mouse model, and we also detected tbc1d32 in the Xenopus otic vesicle, suggesting that TBC1D32 variants may also provoke ciliopathies with deafness associated." (PMID 37768732, 2023). "In agreement with the regulation of ICK and MAK by CCRK, mutations in CCRK and its interacting partner BROMI (also known as TBC1D32) in humans cause ciliopathies, and their mutant/KO mice manifest defective embryonic development caused by dysregulated Hh signaling." (PMID 34624068, 2021). "Remarkably, CFAP20 interacts with disease-causing proteins including: (i) ARL2BP, associated with RP, (ii) TBC1D32 and FOXJ1, related with ciliopathies, and (iii) LRRK2 and DICER1, involved in retinal degeneration in animal models." (PMID 35246562, 2022). "TBC1D32 was found to account for the duplex kidney formation as a part of a ciliopathy phenotype." (PMID 37159529, 2023). "Accordingly, recessive loss-of-function TBC1D32 variants were reported as responsible for oral-facial-digital (OFD) syndrome type IX (OMIM: 258865), a ciliopathy characterized by defects in development of the oral cavity, face, and digits, associated with microphthalmia/anophthalmia." (PMID 37768732, 2023).
acquired immune deficiency syndrome (1 paper, 2020). "Another critical group of proteins interacting with TBC1D32 (13 prey proteins) belongs to acquired immune deficiency syndrome and provides a putative link between the immune system and TBC1D32 function." (PMID 32060556, 2020).
asthma (1 paper, 2024). "Among all candidate genes, the strongest association was found between S. salivarius and rs6917641 located in the intronic region of TBC1D32, a gene previously reported to be genetically associated with a broad range of respiratory disorders including emphysema, asthma, and rhinitis." (PMID 38622589, 2024).
breast carcinoma (1 paper, 2024). "WES analysis of the patient’s breast cancer sample revealed three unique nonsynonymous SNVs in the APOB, TBC1D32, and XAB2 genes." (PMID 38243282, 2024).
congenital hypopituitarism (1 paper, 2020). "To conclude, we describe 3 patients and an aborted fetus with biallelic variants in TBC1D32 ̧ a ciliary gene implicated in SHH signaling and leading to the correct localization of Gli2, a protein that is significantly implicated in the aetiology of congenital hypopituitarism and related disorders." (PMID 32060556, 2020).
diabetes (1 paper, 2024). "The G allele of TBC1D32-rs113987180 was associated with higher risk of ESKD in patients with diabetes (OR:9.879; CI95%:4.440–21.980; P = 2.0E-08)." (PMID 38858654, 2024). "Our findings also highlight variants in TBC1D32 and SURF1 that are associated with a higher risk of ESKD in individuals with diabetes." (PMID 38858654, 2024). "That is the case of TBC1D32, not previously linked to kidney traits, accentuating a high risk of ESKD and emerging as a potential predictor of worse outcome in patients with diabetes." (PMID 38858654, 2024).
Hydrocephalus (1 paper, 2023). Hydrocephalus is an active distension of the ventricular system of the brain resulting from inadequate passage of CSF from its point of production within the cerebral ventricles to its point of absorption into the systemic circulation. "Zebrafish tbc1d32 morphants showed a curvature of the body axis and hydrocephalus, and a TBC1D32-knockout mouse model exhibited neural patterning defects comprising exencephaly, preaxial polydactyly, and poorly developed eyes." (PMID 37768732, 2023).
hypopituitarism (1 paper, 2020). A condition of diminution or cessation of secretion of one or more hormones from the anterior pituitary gland. "Biallelic TBC1D32 variants underlie syndromic hypopituitarism, and the underlying mechanism may be via disrupted Shh signaling." (PMID 32060556, 2020).
Kidney Cyst (1 paper, 2016). Abnormal fluid filled sac within the kidney, either acquired or congenital. "The second class encompassing moderate cystic disease is marked by a few large kidney cysts and is associated with less extensive tubule dilation (Tbc1d32)." (PMID 27002738, 2016).
microcephaly (1 paper, 2020). A congenital or acquired developmental disorder in which the circumference of the head is smaller than normal for the person's age and sex. "To date, biallelic TBC1D32 variants have been described in 1 male patient with severe facial and ocular phenotypes, microcephaly, postaxial polydactyly, and CNS abnormalities, including the absence of the pituitary gland with subsequent panhypopituitarism." (PMID 32060556, 2020).
retinal ciliopathy (1 paper, 2023). "The disrupted ciliogenesis of the RPE and photoreceptors in both the Xenopus and human models leads us to propose that TBC1D32-associated RP is a retinal ciliopathy." (PMID 37768732, 2023).
Retinal dystrophy (1 paper, 2023). Retinal dystrophy is an abnormality of the retina associated with a hereditary process. "It is noteworthy that 1 patient from a Finnish family with compound heterozygous indels in TBC1D32 also exhibited a progressive retinal dystrophy, but this was not further explored." (PMID 37768732, 2023).
TBC1D32 also shares sentences with these, for which no sentence is quoted: Alzheimer disease (1 paper); cleft lip (1); deafness (1); emphysema (1); kidney injury (1); Lyme disease (1); Parkinson disease (1); primary ciliary dyskinesia (1); respiratory disorders (1); retinal degeneration (1); retinitis pigmentosa (1); rhinitis (1).